PRSS35 (serine protease 35)
Synonyms: C6orf158; MGC46520; dJ223E3.1
Tractability: Antibody: UniProt places it where antibodies can reach, with high confidence; UniProt predicts a signal peptide or a membrane-spanning region; its Gene Ontology location is reachable by antibodies, with medium confidence.
Gene: Protein-coding gene on chromosome 6 (83,512,508 to 83,525,704, forward strand). Ensembl gene ENSG00000146250.
Subcellular location: Secreted
Gene Ontology:
Molecular function: protein binding
Cellular component: extracellular region
Genetic constraint (gnomAD): Loss-of-function variants: 14 observed, 14.97 expected, observed/expected ratio (o/e) 0.94, 90% interval 0.62 to 1.46. The upper end of that interval is the gene's LOEUF score, 1.46, which puts it in group 6 of 6, group 1 being the genes least tolerant of losing a copy. Missense variants: 566 observed, 550.1 expected, observed/expected ratio (o/e) 1.03, 90% interval 0.96 to 1.1. Synonymous variants: 199 observed, 201.03 expected, observed/expected ratio (o/e) 0.99, 90% interval 0.88 to 1.11.
Homologues: Orthologues: chimpanzee PRSS35 (99% identical), macaque PRSS35 (95% identical), dog PRSS35 (90% identical), rabbit PRSS35 (87% identical), pig PRSS35 (85% identical), guinea pig PRSS35 (78% identical), rat Prss35 (78% identical), mouse Prss35 (77% identical), tropical clawed frog prss35 (61% identical), zebrafish prss35 (52% identical). Paralogues in human: PRSS23 (47% identical).
Diseases named in the same sentence as PRSS35 in open-access papers:
PRSS35 is named in the same sentence as 14 diseases in open-access papers, as found by Europe PMC text mining. Sharing a sentence is not in itself a finding about the gene and the disease. The quoted sentences say what the papers report.
renal fibrosis (3 papers, 2017 to 2023). A final common manifestation of a wide variety of chronic kidney diseases characterized by glomerulosclerosis and tubulointerstitial fibrosis. "Elevated HE4 inhibits the degradation of collagen I by inhibiting the activity of serine proteases (Prss23 and Prss35) and matrix metalloproteinases (MMP-2 and MMP-9) and accelerates the deposition of type I collagen in the kidneys, leading to renal fibrosis." (PMID 37753112, 2023). "Prss35+ immunostaining was detected in the interstitial fibroblasts of UUO kidneys and was reported as a regulator of renal fibrosis via collagen degradation." (PMID 29109726, 2017).
liver cancer (2 papers, 2023). An epithelial or non-epithelial malignant neoplasm that arises from the liver. "Overexpression of PRSS35 in PLC, HepG2, and Hep3B liver cancer cells further led to the identification of a short form (SF-PRSS35) in the culture medium, suggesting that this short form was specifically secreted." (PMID 36934105, 2023). "Here, by secretome analysis of hepatocyte and liver cancer cell lines, we identify a secreted tumor suppressor, PRSS35, that inhibits HCC progression through cleavage of the chemokine CXCL2, which mediates pro-tumor neutrophil function." (PMID 36934105, 2023). "Western blot (WB) analysis using an antibody that recognizes the N-terminus of PRSS35 indicated that both intracellular and extracellular PRSS35 protein levels were markedly reduced in PLC, HepG2, and Hep3B liver cancer cells, relative to its accumulation in THLE3 cells." (PMID 36934105, 2023).
aortic insufficiency (1 paper, 2021). "Unfortunately, PRSS35 has not been reported to be immune‐related, except in aortic stenosis and aortic insufficiency." (PMID 34755462, 2021).
ovarian carcinoma (1 paper, 2021). A malignant neoplasm originating from the surface ovarian epithelium. "Our results suggest that PRSS35 is upregulated in SKCM tissues, which is consistent with the results obtained from studies on ovarian cancer." (PMID 34755462, 2021).
cancer (3 papers, 2021 to 2023). A tumor composed of atypical neoplastic, often pleomorphic cells that invade other tissues. "In this study, we identify a secreted tumor suppressing protein, PRSS35, and describe its function in controlling neutrophil recruitment and cancer progression." (PMID 36934105, 2023). "In a global secretome analysis to understand the function of the secreted protease PRSS35, the study found that PRSS35 inhibits cancer progression through cleavage of the chemokine CXCL2, thereby interfering with protumor neutrophil function." (PMID 38081362, 2023). "As a member of the serine protease family, PRSS35 may also contribute to the aetiology of several cancers." (PMID 34755462, 2021).
tumor (1 paper, 2023). "Here, we show that the secreted pseudo serine protease PRSS35 functions as a tumor suppressor in HCC." (PMID 36934105, 2023). "Since the tumor-suppressive activity of PRSS35 appeared to depend on the in vivo microenvironment, we focused our study on CXCL2 as a candidate substrate, given its well-established role as a chemokine in the tumor immune microenvironment." (PMID 36934105, 2023). "We found that human-PRSS35 (hPRSS35) overexpression significantly suppressed HepG2 tumor growth in Balb/c-nude mice." (PMID 36934105, 2023). "WB analysis confirmed the inhibitory effects of PRSS35 on CXCL2 protein levels in tumor tissues." (PMID 36934105, 2023). "In order to investigate the effects of PRSS35 degradation of CXCL2 on neutrophil activity in tumor progression in vivo, we generated Hepa1-6 cell lines that stably expressed mPRSS35, mCXCL2, both, or an EV control and separately inoculated these lines subcutaneously into C57BL/6J mice." (PMID 36934105, 2023). "Here the authors show that PRSS35 inhibits HCC progression through proteolytic depletion of CXCL2 and subsequently decreased neutrophil recruitment to tumours." (PMID 36934105, 2023). "Since PRSS35 only exhibited tumor-suppressive effects in mice, but not in the cultured cells, we speculated that some factors in the microenvironment are affected by PRSS35." (PMID 36934105, 2023).
PRSS35 also shares sentences with these, for which no sentence is quoted: hepatocellular carcinoma (2 papers); aortic stenosis (1); brain cancer (1); cardiac interstitial fibrosis (1); cleft lip (1); dilated cardiomyopathy (1); migraine (1); pontocerebellar hypoplasia type 6 (1).